ZNF154 (zinc finger protein 154)
Description:
May be involved in transcriptional regulation.
Synonyms: pHZ-92
Tractability: PROTAC: ubiquitination databases record sites on it.
Gene: Protein-coding gene on chromosome 19 (57,696,275 to 57,709,204, reverse strand). Ensembl gene ENSG00000179909.
Subcellular location: Nucleus
Subcellular location (Human Protein Atlas): Nucleoli fibrillar center; Nucleoplasm
Pathways (Reactome):
Gene expression (Transcription): Generic Transcription Pathway
Gene Ontology:
Molecular function: DNA-binding transcription factor activity, RNA polymerase II-specific; RNA polymerase II cis-regulatory region sequence-specific DNA binding
Biological process: regulation of transcription by RNA polymerase II; negative regulation of DNA-templated transcription; regulation of DNA-templated transcription
Cellular component: nucleus
Genetic constraint (gnomAD): Loss-of-function variants: 6 observed, 7.06 expected, observed/expected ratio (o/e) 0.85, 90% interval 0.46 to 1.62. That is too few expected variants to judge how well the gene tolerates losing a copy. Missense variants: 381 observed, 423.22 expected, observed/expected ratio (o/e) 0.9, 90% interval 0.83 to 0.98. Synonymous variants: 143 observed, 148.72 expected, observed/expected ratio (o/e) 0.96, 90% interval 0.84 to 1.11.
Homologues: Orthologues: chimpanzee ZNF154 (99% identical), macaque ZNF154 (94% identical), mouse Zfy1 (18% identical), zebrafish zfx (18% identical), rat Zfy1 (17% identical), mouse Zfy2 (17% identical), tropical clawed frog zfx (17% identical). Paralogues in human: ZNF256 (68% identical), ZNF772 (46% identical), ZNF551 (46% identical), ZNF792 (45% identical), ZNF418 (44% identical), ZNF587B (43% identical), ZNF773 (42% identical), ZNF304 (42% identical), ZIK1 (40% identical), ZNF419 (40% identical), ZNF134 (40% identical), ZNF549 (37% identical), and 26 more.
Diseases named in the same sentence as ZNF154 in open-access papers:
ZNF154 is named in the same sentence as 43 diseases in open-access papers, as found by Europe PMC text mining. Sharing a sentence is not in itself a finding about the gene and the disease. The quoted sentences say what the papers report.
bladder cancer (11 papers, 2012 to 2026). "Methylation levels of EOMES, HOXA9, POU4F2, TWIST1, VIM, and ZNF154 in urine specimens are promising diagnostic biomarkers for bladder cancer recurrence surveillance." (PMID 23056278, 2012). "Epigenetic silencing of ZNF154 was associated with multiple cancers and could serve as a biomarker predicting the recurrence of alcohol-associated pancreatic cancer, as well as non-alcohol-associated prostate cancer and bladder cancer." (PMID 36861126, 2023). "In urine samples, the methylation status of a urinary biomarker panel (HOXA9, ONECUT2, PCDH17, PENK, TWIST1, VIM, and ZNF154) showed great prediction accuracy in predicting bladder cancer in patients with hematuria." (PMID 37627900, 2023). "Hypermethylation of ZNF154 has also been identified in hepatocellular carcinoma, and as part of a panel of early detection biomarkers in DNA from voided urine of bladder cancer patients." (PMID 37254212, 2023). "The methylation status of a 4-gene panel (HOXA9, EOMES, POU4F2, and ZNF154) was significantly different between urine samples from bladder cancer patients and healthy individuals." (PMID 37627900, 2023). "In another study, the correlation between the methylation levels of EOMES, HOXA9, POU4F2, TWIST1, VIM, and ZNF154 in urine specimens and bladder cancer recurrence surveillance was discovered by real-time PCR." (PMID 33388091, 2021). "ZNF154 hypermethylation is a urine-based prognostic biomarker for bladder cancer, where hypermethylation correlates with recurrence-free survival of the patients." (PMID 31379917, 2019). "Here, we established a combination methylation assay of HOXA9, ONECUT2, PCDH17, PENK, TWIST1, VIM and ZNF154, which had displayed great prediction accuracy of bladder cancer in patients with hematuria by using urine samples." (PMID 31777606, 2019). "In this study we performed an independent validation of EOMES, HOXA9, POU4F2, TWIST1, VIM, and ZNF154 methylation for the urinary diagnosis in bladder cancer surveillance." (PMID 23056278, 2012). "Furthermore, ZNF154 was originally reported as a methylation marker specific for bladder cancer, later showing relevance in many cancer types." (PMID 37835520, 2023). "In addition, a 6-gene panel (HOXA9, EOMES, POU4F2, TWIST1, VIM, and ZNF154) was highly hypermethylated in the urine of bladder cancer patients as compared to healthy individuals." (PMID 37627900, 2023). "In conclusions, a urinary combined methylation assay of HOXA9, ONECUT2, PCDH17, PENK, TWIST1, VIM and ZNF154 displayed accurate prediction of bladder cancer in hematuria patients, which provided the guidance for the patients at early stage tumor and during the follow-up after operation." (PMID 31777606, 2019). "Reinert and collaborators established a detailed mapping of the methylome in bladder cancer and identified four novel DNA methylation marks: HOXA9, ZNF154, POU4F2, and EOMES." (PMID 22829811, 2012). "However, in this study the ZNF154 marker failed to diagnose two muscle-invasive bladder cancers that progressed from two T1 grade III tumors." (PMID 23056278, 2012).
ovarian carcinoma (7 papers, 2015 to 2026). A malignant neoplasm originating from the surface ovarian epithelium. "Methylation-mediated repression of ZNF154 in ovarian cancer is associated with poor overall survival." (PMID 25716334, 2015). "ZNF154 was validated as a reliable marker, offering a cost-effective and efficient method for assessing ovarian cancer cell fraction using pyrosequencing." (PMID 37629546, 2023). "SIM1 and ZNF154 genes were identified as potential methylation markers for ovarian cancer cell fraction estimation." (PMID 37629546, 2023). "We previously showed that ZNF154 methylation detection in ovarian cancer plasma outperformed patient CA-125 measurement (69.6% vs. 47.8%, correct classification, respectively), and combined, the two markers showed improvement over ZNF154 alone (87.0%, correct classification)." (PMID 37835520, 2023). "Furthermore, we demonstrated that EpiClass analysis of ZNF154 methylation was able to outperform CA-125 in the detection of etiologically diverse ovarian carcinomas, indicating broad utility of ZNF154 for use as a biomarker of ovarian cancer." (PMID 33081832, 2020). "Likewise, ZNF154 methylation appears to be useful for detection and monitoring of EOC subtypes, in contrast to CA-125, which is largely limited to only serous-type ovarian carcinomas." (PMID 33081832, 2020).
prostate carcinoma (7 papers, 2016 to 2023). A carcinoma that arises from epithelial cells of the prostate gland. "In contrast, a different research group reported poor outcomes in loss of function of ZNF154 in prostate cancer." (PMID 31683647, 2019). "Kaplan–Meier analysis has also shown that ZNF154 methylation level was associated with biochemical recurrence (BCR) (p = 0.005) in prostate cancer, and that ZNF154 could be an independent factor for BCR prediction by using univariate and multivariate Cox regression analysis (p = 0.035, HR = 8.218)." (PMID 37254212, 2023). "Hypermethylation of ZNF154 has been reported in breast, lung, hepatocellular, ovarian, renal and prostate cancer." (PMID 29156753, 2017). "It has been proven that the hypermethylation and low expression of ZNF154 in different solid tumors, including prostate cancer and nasopharyngeal carcinoma, could be a predictive marker." (PMID 34452548, 2021).
pancreatic cancer (6 papers, 2019 to 2024). "Curiously, an opposite association was observed in pancreatic cancer patients who had undergone a pancreatic resection, where a silenced ZNF154 gene was actually associated with a better patient survival." (PMID 37254212, 2023). "Increased survival rates in pancreatic cancer patients were associated with the silencing of ZNF154, which, in turn, led to increased levels of SLFN5." (PMID 37771431, 2023). "For example, in this study, ZNF154 methylation outperformed KRAS mutations in pancreatic cancer, when counts of any methylated ZNF154 fragment were used to classify cancer versus control plasma samples." (PMID 33420235, 2021). "Taken together, we are the first, to our best knowledge, to report an association between hypermethylation of the ZNF154 promoter and better survival in resectable pancreatic cancer." (PMID 31683647, 2019). "We found a significant association between ZNF154 hypermethylation and better survival in patients with resectable pancreatic cancer." (PMID 31683647, 2019). "The ability of ZNF154 methylation to outperform KRAS mutations for the detection pancreatic cancer in patient plasma may reflect technical differences between the assays used and biological differences between DNA methylation and mutations." (PMID 33420235, 2021). "Thus, it is suggested that SLFN5 may play a role in pancreatic cancer and is associated with the upregulation or downregulation of the ZNF154 gene." (PMID 37771431, 2023). "Moreover, we suspect that the cell growth suppressor SLFN5 might be linked to a silenced ZNF154 in pancreatic cancer." (PMID 31683647, 2019). "ZNF154 cfDNA methylation discriminated cases from healthy donor plasma samples in minimal plasma volumes and outperformed KRAS mutation frequency in pancreatic cancer." (PMID 33420235, 2021). "Analysis of methylation at ZNF154 is considerably simpler, cheaper, and faster than CancerSEEK, and achieves similar detection sensitivity with respect to colorectal and pancreatic cancer detection by only using a single genomic locus." (PMID 33420235, 2021). "In the present study, we demonstrated a positive correlation between silenced ZNF154 and prolonged survival in resectable pancreatic cancer patients." (PMID 31683647, 2019). "To investigate a possible presence of ZNF154 hypermethylation in vivo, we analyzed pancreatic cancer specimens from 80 patients." (PMID 31683647, 2019). "More specifically, we aimed to analyze pancreatic tumor tissue samples from patients who received pancreatic resection for ZNF154 hypermethylation and to further characterize the effect of ZNF154 hypermethylation in vitro." (PMID 31683647, 2019). "Furthermore, exogenous expression of ZNF154 in pancreatic cancer cells revealed increased SLFN5 expression, indicating a novel link between SLFN5 and ZNF154." (PMID 38791884, 2024). "That same study demonstrated that ZNF154 circulating-free DNA (cfDNA) methylation discriminated cases from healthy donor plasma samples and outperformed KRAS mutation frequency as a biomarker in pancreatic cancer." (PMID 37254212, 2023). "Above, we found that ZNF154 hypermethylation in Illumina methylation array data (90.7%) was as frequent as KRAS mutations (90.7%) for the PAAD samples, making pancreatic cancer an interesting case study for comparing the utility of the two markers for classifying samples from blood." (PMID 33420235, 2021). "Hence, the usefulness of ZNF154 in screening for pancreatic cancer should be reassessed with a different patient collective for this matter." (PMID 31683647, 2019). "Moreover, ZNF154 may be particularly helpful in detecting early-stage disease (AUC for early stage was 0.87), as shown for this small sample size of pancreatic cancers." (PMID 33420235, 2021). "Hence, we argue that SLFN5 might play a role in pancreatic cancer and is connected to up- or downregulation of the ZNF154 gene." (PMID 31683647, 2019).
pancreatic cancer (continued). "For these reasons, we decided to conduct a head-to-head comparison of ZNF154 hypermethylation versus KRAS mutation for classifying plasma samples taken from individuals with and without pancreatic cancer." (PMID 33420235, 2021). "We performed a single-molecule high-resolution DNA melt analysis on 71 plasma samples from cancer patients and 20 noncancer individuals to assess ZNF154 methylation as a candidate diagnostic metric in liquid biopsy and compared results to KRAS mutation frequency in the case of pancreatic carcinoma." (PMID 33420235, 2021). "Moreover, we suspect a link between a silenced ZNF154 and SLFN5 in pancreatic cancer." (PMID 31683647, 2019).
gastric cancer (4 papers, 2021 to 2024). A primary or metastatic malignant neoplasm involving the stomach. "In addition, ZNF154 was found to be a tumor suppressor gene, and its low expression was associated with the poor prognosis of gastric cancer." (PMID 38801557, 2024). "By contrast, ZNF154 displayed the largest amount of differential methylation for stomach cancer (difference in median methylation 0.63), improving performance over TLX1 or GALR1 (difference in median beta value at 0.50 and 0.30, respectively)." (PMID 37835520, 2023). "And most recently, expression of ZNF154 in MGC-803 gastric cancer cells reduced cell proliferation, viability, migration and invasion, and enhanced cell apoptosis and arrested cell cycle in G2 phase." (PMID 37254212, 2023). "SORCS3, ZNF154 and ZNF177 are hypermethylated in gastric cancers, while ZNF177 is also hypermethylated in hepatocellular carcinomas." (PMID 34882728, 2021).
hepatocellular carcinoma (4 papers, 2020 to 2023). A malignant tumor that arises from hepatocytes. "In patient plasma from hepatocellular carcinoma, ZNF154 alone yielded the highest combined sensitivity and specificity values averaging 68% and 72%, whereas multiple markers could achieve higher sensitivity or specificity, but not both." (PMID 37835520, 2023). "Notably, applying EpiClass to ZNF154 methylation in the context of WGBS data from HCC patient and normal control plasma samples demonstrated promise for detecting early stage hepatocellular carcinoma as 25 out of the 30 WGBS datasets were collected from patients with early stage disease." (PMID 33081832, 2020).
nasopharyngeal carcinoma (4 papers, 2019 to 2023). A carcinoma arising from the nasopharyngeal epithelium. "A recent study has shown that ZNF154 methylation was associated with better survival in nasopharyngeal carcinoma." (PMID 31683647, 2019).
liver cancer (3 papers, 2020 to 2023). An epithelial or non-epithelial malignant neoplasm that arises from the liver. "Using the common threshold for classification of all tumor types as one disease, and then zooming in on the liver cancer cohort, ZNF154 showed the best sensitivity of all single markers at 77%." (PMID 37835520, 2023). "Using this data, we assessed methylation at our locus of interest, ZNF154, and three additional liver cancer loci, using both methods." (PMID 33081832, 2020). "Applying this technology on the sequenced plasma samples derived from patients with liver cancer or healthy controls, we found that ZNF154 and TLX1 performed with similar sensitivity (20% and 21%, respectively) when forcing the specificity to its maximum level (93% and 94%, respectively)." (PMID 37835520, 2023). "Importantly, ZNF154 enabled near-perfect classification of liver cancer samples with an AUC of 0.92, whereas GALR1 and TLX1 only produced AUC values of 0.64 and 0.77, respectively." (PMID 37835520, 2023). "For example, in TCGA liver cancer tissue data, ZNF154 alone could obtain a sensitivity of 87% and specificity of 98% with an AUC value at 0.92." (PMID 37835520, 2023). "Additionally, the agreement of the methylation density cutoffs between our different sample cohorts implies that localized discordant methylation profiles are possibly a product of consistent underlying biological phenomena as observed here in the case of EOC and liver cancer at the ZNF154 locus." (PMID 33081832, 2020).
lung adenocarcinoma (3 papers, 2021 to 2023). A carcinoma that arises from the lung and is characterized by the presence of malignant glandular epithelial cells. "Low ZNF154 and low ZNF132 expression were associated with shorter overall survival in both head and neck squamous cell carcinoma (HNSCC) and lung adenocarcinoma (LUAC patients)." (PMID 37254212, 2023). "The prognostic value of ZNF154 and ZNF132 expression was similarly observed in patients from the lung adenocarcinoma (LUAD) TCGA patient cohort." (PMID 37254212, 2023).
breast carcinoma (2 papers, 2021 to 2023). "Indeed, the hypermethylation of ZNF154 in the tissue samples and plasma collected in the early stages of different solid tumors, including breast cancer is consistent with our data." (PMID 34452548, 2021). "In summary, the results showed that the methylation pattern of HOXD9, ZNF154, and BCL9 genes in peripheral blood leukocytes could be used as a potential biomarker for breast cancer risk assessment." (PMID 34452548, 2021). "A total of 1799 differentially methylated regions were identified, including ZNF154, BCL9, and HOXD9, in which significant methylation differences were confirmed in breast cancer patients through a quantitative real-time polymerase chain reaction." (PMID 34452548, 2021). "Three novel DMRs located in promoter regions of HOXD9, ZNF154, and BCL9 genes were confirmed in the peripheral blood of breast cancer patients." (PMID 34452548, 2021).
colon cancer (2 papers, 2021 to 2023). "While GALR1 and TLX1 showed near perfect performance in classifying colon cancer (AUC of 0.97 for both), ZNF154 only achieved an AUC of 0.81 within this tumor type." (PMID 37835520, 2023). "A good example of the compromise between sensitivity and specificity when settling on a threshold is the performance of ZNF154 in colon cancer." (PMID 37835520, 2023). "With respect to the liver and colon cancer sample sets, each had higher median normalized fragments of methylated ZNF154 cfDNA (14.56/mL and 64.49/mL, respectively) than the controls, although this was not significant, likely a result of the small size of these cohorts." (PMID 33420235, 2021).
esophageal squamous cell carcinoma (2 papers, 2019 to 2023). Esophageal squamous cell carcinoma (ESCC) is a type of esophageal carcinoma (EC) that can affect any part of the esophagus, but is usually located in the upper or middle third. "We further identified 406 promoter methylation target loci associated with patients survival, including known esophageal squamous cell carcinoma biomarkers, cg03234186 (ZNF154), and cg02587316, cg18630667, and cg05020604 (ZNF382)." (PMID 31379917, 2019). "However, a recent support supporting a tumour suppressive role for ZNF154 included data showing that targeted expression of ZNF154 inhibited expression of esophageal squamous cell carcinoma cells in vivo." (PMID 37254212, 2023).
head and neck cancer (2 papers, 2023). A primary or metastatic malignant neoplasm affecting the head and neck. "Both ZNF132 and ZNF154 represent novel clinically significant biomarkers in head and neck cancer with potential tumour suppressive properties." (PMID 37254212, 2023). "On the other hand, ZNF154 showed optimal performance in several other cancers such as uterine corpus endometrial and head and neck cancer." (PMID 37835520, 2023). "We examined prognostic significance of ZNF154 and ZNF132 expression and DNA methylation in independent patient cohort of about 500 head and neck cancer patients in the Cancer Genome Atlas (TCGA)." (PMID 37254212, 2023). "The epigenetic silencing of ZNF154 and ZNF132 were not confined to head and neck cancers." (PMID 37254212, 2023).
serous ovarian cancer (2 papers, 2015 to 2020). "Of additional note, CA-125 misclassified all of the patients with non-serous ovarian cancer subtypes (n = 9), whereas EpiClass-thresholded ZNF154 correctly classified 6 of the 9 endometrioid samples." (PMID 33081832, 2020). "Hypermethylation at the CpG island in the promoter region of ZNF154, and negative correlation between methylation and gene expression were recently described in serous ovarian cancers, and in endometrioid ovarian and endometrial cancers." (PMID 25716334, 2015).